MIEN1 (migration and invasion enhancer 1)
Diseases named in the same sentence as MIEN1 in open-access papers (continued):
Sharing a sentence is not in itself a finding about the gene and the disease.
cancer (continued). "Sequencing demonstrated that MIEN1 promoter have SINE Alu repeat.Study indicated that in cancer cells, due to hypomethylation of SINE Alu provides USF binding which results in MIEN1 expression." (PMID 31552186, 2019). "Recently, MIEN1 protein was found to localize in a concerted manner beneath the action protrusion structures of migratory cancer cells." (PMID 31552186, 2019). "Limited information is available assessing the role of MIEN1 in various human malignancies, suggesting the demand for additional well-designed studies to evaluate its functional role in cancer." (PMID 31552186, 2019). "We also highlight future prospects of MIEN1 as novel drug target against cancer cell invasion and metastasis." (PMID 31552186, 2019). "High-mobility group box 2 (HMGB2) binding protein interacts with MIEN1 and enhances cancer progression and proliferation." (PMID 35582722, 2019). "In the present review, we discuss the structure, function, and involvement of MIEN1 in cancer progression." (PMID 31552186, 2019). "Emerging literature suggest MIEN1 as a new tumor-specific target protein as it facilitates cancer progression that plays key role in distinct processes of migration/invasion of cancer cells." (PMID 31552186, 2019). "We also highlight the future prospects of MIEN1 as an emerging molecule and novel target in cancer cell invasion and metastasis." (PMID 31552186, 2019). "Knocking out MIEN1 in these cancer cells allows us to study the effect of its absence from a background where it is normally expressed rather than over-expressing it in a cell line which does not have endogenous expression." (PMID 30286132, 2018). "Migration and Invasion Enhancer (MIEN1) is an oncogene which is involved in facilitating motility of cancer cells through actin dynamics and gene expression." (PMID 30286132, 2018). "Given the importance of MIEN1 in various cancers, determining the regulator(s) that maintain its levels during disease-free homeostasis is essential to enable its use as a target." (PMID 27589566, 2016). "Studies previously conducted by our lab and other groups have identified migration and invasion enhancer 1 (MIEN1) as an important gene involved in cancer progression." (PMID 27589566, 2016). "Together, these results demonstrate that the methylation of SINE Alu region in the MIEN1 putative promoter is definitely lost in cancer compared to normal cells, thus supporting the known phenomena of global hypomethylation in cancer." (PMID 27589566, 2016). "Together, our results prove that MIEN1 promoter methylation is very important in repressing the gene in normal cells and that this regulation is lost in cancer." (PMID 27589566, 2016). "Previous studies have attributed a role to MIEN1 in tumor cell migration by inducing filopodia formation and subsequent dissemination of cancer cells to distant organs." (PMID 27462783, 2016). "Our study shows that the MIEN1 promoter has a SINE Alu region that is hypomethylated in cancer, resulting in an increased expression of MIEN1 in cancer." (PMID 27589566, 2016). "All together, these results clearly show that MIEN1 is concentrated in the cytoplasm of migrating cancer cells and localized to focal adhesions." (PMID 27462783, 2016). "This would imply the presence of this region (around 550 bases from the transcription start site of MIEN1) to be a strong indicator of lower methylation in cancer." (PMID 27589566, 2016). "In normal cells, the SINE Alu region in the MIEN1 promoter is methylated thus keeping the transcription of this gene under check; but in cancer, the hypomethylation results in transcriptional activation of the gene." (PMID 27589566, 2016). "A novel miRNA, hsa-miR-940 (miR-940), identified and validated to be highly expressed in immortalized normal cells compared to cancer cells, is a regulator of MIEN1." (PMID 25406943, 2014).
cancer (continued). "MIEN1, a novel gene in the 17q12 region of the human chromosome, is differentially expressed between cancer and normal cells and tissues." (PMID 25406943, 2014). "Migration and invasion are key processes that facilitate cancer progression and MIEN1 is known to increase these processes." (PMID 25406943, 2014). "Together, these results demonstrate that miR-940 is differentially expressed between normal and cancer cells and that it targets and regulates MIEN1 expression." (PMID 25406943, 2014). "MIEN1 locates within the minus strand of the human chromosomal region 17q12-21, a “hot spot” locus of cancer named HER2 amplicon." (PMID 23284973, 2012). "Through in vivo and ex vivo experiments, we demonstrated that CTCF promotes the transcription of Migration and Invasion Enhancer 1 (MIEN1), enhancing neutrophil migration toward cancer cells, and stimulates IL-1β secretion, leading to a malignant phenotype in CRC cells." (PMID 40959269, 2025). "Geranylgeranylation of MIEN1 at the CVIL motif enables the protein to associate with the inner leaflet of the plasma membrane and induces filopodia formation, promoting migration of cancer cells." (PMID 38272230, 2024). "Besides this, migration and invasion enhancer 1 (MIEN1), responsible for cancer cell migration, is also inhibited." (PMID 36839985, 2023). "Considering their previous study, the authors hypothesized that miR-940 might be exported from cancer cells to prevent the downregulation of MIEN1 and other predicted target proteins that promote cancer progression." (PMID 34503302, 2021). "Below we summarize studies which shed light on the involvement of MIEN1 protein in various cancers." (PMID 31552186, 2019). "MIEN1 has been identified as a primary regulator of cancer cell migration and invasion." (PMID 31552186, 2019). "Studies on MIEN1 have shown its role in promoting drug resistance in some cancer types." (PMID 31552186, 2019). "MIEN1-mediated increase in focal adhesion kinase (FAK) and decrease in cofilin phosphorylation at Tyr-925 and Ser-3 are associated with actin dynamics and cellular adhesion in migratory cancer cells." (PMID 31552186, 2019). "Thus, the differerential expression of MIEN1 in normal vs. cancer cells proposes it to be a novel tumor biomarker." (PMID 31552186, 2019). "MIEN1 expresses differentially in normal cells and cancer cells." (PMID 35582722, 2019). "However, this does not explain nor does it negate the possibility of an inherently higher transcriptional activation of MIEN1 in cancer compared to normal cells." (PMID 27589566, 2016). "Also, from our results and findings from TCGA, we can conclude that methylation of MIEN1 plays both an important role in the gene regulation as well as diagnosis of cancer, albeit through different sites." (PMID 27589566, 2016). "Our findings place MIEN1 and anxA2 as attractive therapeutic targets for blocking invasive cancers." (PMID 26272794, 2015). "Our previous studies identified MIEN1 as the prime regulator of cancer cell migration and invasion." (PMID 26272794, 2015). "MIEN1 is minimally expressed in several normal tissues compared to its overexpression in cancer." (PMID 25406943, 2014). "MIEN1 is differentially expressed between normal and cancer cells and tissues." (PMID 25406943, 2014). "In contrast, the minimal MIEN1 expression found in 38 different normal tissues examined suggests that MIEN1 is a cancer-specific protein and could be a novel tumor biomarker." (PMID 23284973, 2012). "On the one hand, it cripples the cancer cell migration and invasion and on the other hand, it inhibits the NF-κB induced EMT in cancer cells.LA3IK and RP-7 exhibited distinct interactions with the MIEN1 protein, evident in noticeable deviations in CD spectra." (PMID 38272230, 2024). "Because of the importance of MIEN1 in cancer progression and metastatic events, producing CRISPR mediated MIEN1 KO cells will allow us to better understand the role of MIEN1 in these various processes." (PMID 30286132, 2018).
cancer (continued). "It was reported in many studies that miR-940 was highly expressed in normal tissues compared with tumors, and miR-940 was shown to inhibit the migratory and invasive potential of cancer cells by suppressing CXCR2, MIEN1, MyD88, Nestin, and ZNF24." (PMID 28423620, 2017). "In cancer, the hypomethylation of a part of this repeat, in addition to the binding of USF, results in MIEN1 expression." (PMID 27589566, 2016). "MIEN1 is located in the 17q12 region of the human chromosome, alongside HER2/neu, a region of extreme importance in various cancers." (PMID 27589566, 2016). "However, the functional significance of MIEN1 in cancer biology remained largely unknown." (PMID 23284973, 2012). "Development of small molecule inhibitors specifically targeting MIEN1 in cancer has not yet been reported." (PMID 31552186, 2019). "MIEN1 is a membrane-anchored protein located in the 17q12 region of the human chromosome which is 505 nucleotide upstream to 3′ ERBB2 oncogene, inside the hot-spot locus of cancer." (PMID 31552186, 2019). "Taken together, these studies confirm that MIEN1 plays an important role in the progression of cancer rather than in the initiation of the tumor." (PMID 25406943, 2014). "Overexpression of MIEN1 and TRAF4 has been reported in various cancers and functionally regulates the PI3K/AKT pathway to promote tumorigenesis, and therefore, this overexpression may contribute to the dysregulated PI3K/AKT signaling pathway observed in refractory MCLs." (PMID 34001881, 2021). "Studying the roll of MIEN1 in cancer progression can be accomplished by a variety of methods; however, genomic deletion using the CRISPR-Cas9 system offers the ability to examine the functional significance of MIEN1 knockout (MKO) in a background in which it is endogenously expressed." (PMID 30286132, 2018). "Hence, the increase expression of MIEN1 in the immortalized normal epithelial cells, with no similar increase in cancer cells, implies complete demethylation instead of hemimethylation in cancer." (PMID 27589566, 2016). "The expression of miR-221 and miR-324-3p were neither consistently higher in the immortalized cells compared to the cancer cells, nor were they significantly different, together indicating that miR-940 may be the most relevant regulator of MIEN1 among the three miRNAs." (PMID 25406943, 2014).
tumor (24 papers, 2010 to 2025). "MIEN1 expression is elevated in colorectal cancer tissues and is closely associated with tumor serous invasion, lymph node metastasis, and advanced Dukes stage." (PMID 40104500, 2025). "Physiologically, MIEN1 is associated with the formation of filopodia to accelerate cellular motility during tumor dissemination, in addition to controlling cell apoptosis." (PMID 34066014, 2021). "Any association of MIEN1 with normal cell development will lead to challenges in acquiring tumor cell specificity." (PMID 31552186, 2019). "We investigated the potential interacting partners of MIEN1 to define the mechanisms associated with tumor cell migration and invasion." (PMID 26272794, 2015). "The overexpression of PGAP3 and MIEN1 has been linked to metastasis in BC patients, suggesting that they could be therapeutic targets for combating tumor spread." (PMID 40136626, 2025). "While MIEN1 has been studied extensively in tumor biology, its involvement in neutrophil chemotaxis has been poorly characterized." (PMID 40959269, 2025). "Functionally, CTCF modulated neutrophil survival, ribosomal function, and recruitment toward tumor cells through MIEN1." (PMID 40959269, 2025). "Specific proteins, such as MIEN1, further enhance migration, collectively contributing to tumor invasiveness." (PMID 40168262, 2025). "The higher level of MIEN1 enhances tumor growth and actin reorganization inducing phosphorylation of focal adhesion kinase (FAK) at tyrosine-925 and reducing cofilin phosphorylation at serine-3." (PMID 38272230, 2024). "Several studies have shown that MIEN1 overexpression results in either disease progression or metastatic propensity in many tumor types, including colon, prostate, ovarian, non-small cell lung, stomach, and oral cancers." (PMID 31581708, 2019). "In patients with metastatic breast cancer, aberrant expression of MIEN1 has been noted in distant metastatic sites such as lungs and liver, suggesting a possible role of MIEN1 protein in metastatic dissemination of tumor cells." (PMID 31552186, 2019). "Depletion of MIEN1 reduced tumor cell migration in wound closure assay at 9 h compared to control siRNA treated MDA-MB-231 cells by almost 40%." (PMID 27462783, 2016). "While increased MIEN1 facilitates tumor progression, its expression is low to negligible in various normal cells and tissues, making MIEN1 an attractive biomarker and therapeutic target." (PMID 27589566, 2016). "MIEN1 overexpression represents an oncogenic event that promotes tumor cell dissemination and metastasis." (PMID 27462783, 2016). "Fluorescence resonance energy transfer (FRET) confirmed that MIEN1 physically interacts with AnxA2 and functional studies revealed that they mutually cooperate to accentuate tumor cell motility." (PMID 26272794, 2015). "Here we report the dynamics of MIEN1-induced signaling that regulate tumor cell migration and invasion." (PMID 26272794, 2015). "We performed several assays including co-immunoprecipitation, wound healing, western blotting and immunofluorescence to decipher the molecular events involved in MIEN1-mediated tumor cell migration." (PMID 26272794, 2015). "MIEN1 is considered an oncogenic protein, because MIEN1 overexpression functionally enhances migration and invasion of tumor cells via modulating the activity of AKT." (PMID 23284973, 2012). "Confirming the CNV-by-exome analysis, ddPCR analysis of Grb7 and Mien1, which are located close to Erbb2 in both mouse and human (the locus is syntenic in the two species), demonstrated similar levels of amplification in the tumours to Erbb2/Neu." (PMID 34003256, 2021). "In conclusion, advances in the understanding of MIEN1 biochemistry and MIEN1 tumor biology over years, together with technological advancement in therapeutic targeting approaches, should lead to further in vivo validation of the anticancer benefits of targeting MIEN1 and associated proteins." (PMID 31552186, 2019).
tumor (continued). "However, the exact molecular events at the membrane interface activating the MIEN1-driven tumor cell motility are vaguely understood." (PMID 26272794, 2015). "The redox potential of MIEN1 was found between that of thioredoxin and protein disulfide isomerase (−175 mV), so MIEN1 may catalyze the reduction and/or isomerization of disulfide bonds for tumor-related proteins." (PMID 23284973, 2012). "It has been found that increased expression of MIEN1 might enhances tumor migration and metastasis." (PMID 33926574, 2021). "Thus, MIEN1-AnxA2 protein-protein interaction might be regarded as one of the mechanisms facilitating tumor metastasis." (PMID 31552186, 2019). "In an orthotopic CRC mouse model, CTCF-over-expressing TANs increased tumor growth and TAN infiltration, which was attenuated by MIEN1 knockdown or IL-1β neutralization." (PMID 40959269, 2025). "Two proteins that interact with HMGB2, COMMD1 and MIEN1, are identified in SKOV-3 and tumor tissue libraries, which cross-validate these results." (PMID 32867128, 2020). "Our findings reveal a novel, non-inflammatory MIEN1-dependent mechanism by which TANs are drawn toward tumor cells—potentially allowing immune cell infiltration without triggering tumor-damaging inflammatory responses." (PMID 40959269, 2025). "While the expression levels of GRB7, MIEN1, ERBB2 and FBXL20 were considerably greater in tumour tissues than in normal tissues (p < 0.001 or p < 0.01), the expression levels of MED1 and CDK12 were significantly lower in tumour tissues than in normal tissues (p < 0.001)." (PMID 37525498, 2023). "Our previous study has shown that cells overexpressing MIEN1 have a higher metastatic potential, though it does not mean quicker onset or initiation of the tumor." (PMID 25406943, 2014). "Moreover, the results also inferred no apparent discrepancies in tumor proliferation, morphology or vitality between the MIEN1 KO cells and the original cell lines." (PMID 34066014, 2021).
adenocarcinoma (1 paper, 2019). A common cancer characterized by the presence of malignant glandular cells. "The results of immunohistochemical analysis indicated that MIEN1 was expressed specifically in epithelial cells and significantly higher in adenocarcinoma as compared to in normal tissues." (PMID 31581708, 2019).
MIEN1 also shares sentences with these, for which no sentence is quoted: gastric cancer (2 papers); invasive breast carcinoma (2); benign prostatic hyperplasia (1); breast ductal carcinoma (1); colitis (1); esophageal cancer (1); hematological malignancies (1); hyperphosphatemia (1); intellectual disabilities (1); melanoma (1); pancreatic ductal adenocarcinoma (1); polycystic ovary syndrome (1); transitional cell carcinoma (1); triple-negative breast carcinoma (1).